AR (androgen receptor)
Diseases named in the same sentence as AR in open-access papers (continued):
Sharing a sentence is not in itself a finding about the gene and the disease.
prostate carcinoma (continued). "With the increases in Cao2+ concentration in the lower chamber, we found that DU145 and PC-3, the AR- deficient and highly metastatic prostate cancer cell lines, had increased numbers of migrating cells in the presence of elevated Cao2+ (3 mM) versus low Cao2+ (50 μM)." (PMID 27206800, 2017). "Therefore, we performed the present meta-analysis aimed to provide a more precise and comprehensive result for the relationship between CAG and GGN repeat polymorphisms of androgen receptor gene and prostate cancer susceptibility." (PMID 28091563, 2017). "Therefore, the correlation between these polymorphisms of androgen receptor and risk of prostate cancer has received much attention." (PMID 28091563, 2017). "Their meta-analysis demonstrated that the CAG repeat polymorphism in androgen receptor gene with more than 20 repeats might confer a protective effect among the prostate cancer cases among men 45 years or older only." (PMID 28091563, 2017). "The reason underlying the loss of stromal AR with prostate cancer progression is unclear." (PMID 29181019, 2017). "In a previous population-based study on 3369 European men with self-reported prostate cancer (PCa), it was shown that androgen receptor (AR) haplotype designated H2 was associated with high levels of serum PSA (prostate-specific antigen) concentration, and, at the same time, with low risk for PCa." (PMID 28176139, 2017). "It was reported that 1 nM BPA treatment induces cell proliferation in human prostate cancer cells LNCaP which contain an androgen receptor (AR) point mutation (AR-T877A) frequently associated in patients with advanced prostate cancers refractory to hormone therapy." (PMID 29383186, 2017). "Whether CaR-mediated signaling is involved in filamin A cleavage and regulating migration in AR-deficient and highly metastatic prostate cancer cells is still unknown." (PMID 27206800, 2017). "Deregulated androgen receptor (AR) signaling due to either mutations or altered expression of the AR and its cofactors (activators or suppressors) have also been identified as a critical factors in prostate cancer development, progression and metastasis." (PMID 28439080, 2017). "The current study has discovered that USP14, one of the 19S proteasome-associated DUBs, is involved in the stabilization of AR proteins and promotes G0/G1 to S phase transition in human prostate cancer cells and also identified USP14 as a potential target for prostate cancer therapy." (PMID 28151478, 2017). "The androgen receptor (AR) transcription factor plays a key role in the development and progression of prostate cancer, as is evident from the efficacy of androgen-deprivation therapy, AR is also the most frequently mutated gene, in castration resistant prostate cancer (CRPC)." (PMID 28570625, 2017). "In addition, it specifically repressed global OCT1 chromatin association and AR signaling in prostate cancer cells." (PMID 28264478, 2017). "Early studies have linked H2A deubiquitination to prostate cancer where MYSM1 regulated androgen receptor-dependent gene activation by coordinating histone acetylation and deubiquitination, and destabilizing the association of linker histone H1 with nucleosomes." (PMID 28978033, 2017). "Understanding the CaR- mediated signaling pathway that is involved in prostate cancer cell migration could lead to new targets for drug development and therapeutic strategies for AR- deficient prostate cancer and recurrence of prostate cancer after ADT." (PMID 27206800, 2017). "Androgen receptor variants (AR-Vs) provide a mechanism of therapy evasion in castrate-resistant prostate cancer (CRPC), yet mechanisms of regulation remain largely unknown." (PMID 28205582, 2017).
prostate carcinoma (continued). "In particular, eligibility requirements for the prostate cancer trial required castrate levels of serum testosterone (≤50 ng/mL), and decreased AR-activity may have caused a downregulation of SLC35F2 that prevented effective tumor uptake of YM155." (PMID 28350329, 2017). "Furthermore, Cao2+-induced filamin A cleavage is a CaR- p115RhoGEF-calpain dependent process, and the cleavage of filamin A promotes the migration of AR- deficient and highly metastatic prostate cancer cells." (PMID 27206800, 2017). "To determine whether urinary EVs could be used to examine other genes associated with prostate cancer we investigated the differential expression of androgen receptor (AR), BIRC5, ERG, PCA3, TMPRSS2:ERG and TMPRSS2 in Bx Pos versus Bx Neg patients." (PMID 27144529, 2016). "To examine whether other variant forms of AR may exist, we amplified the AR from various breast and prostate cancer cell lines by RT-PCR using primers located in the canonical exon 1 and exon 8, and then cloned and sequenced a set of the PCR products." (PMID 28035996, 2016). "Interestingly, although independent from MTA1, pterostilbene also downregulated the AR levels, further strengthening its potential as a suitable chemopreventive agent to reduce the risk of prostate cancer." (PMID 26943043, 2016). "While somatic mutations in the androgen receptor are a known mechanism of acquired hormone therapy resistance in prostate cancer, somatic mutations in ESR1 have only recently been identified as an important mechanism of acquired endocrine therapy resistance in breast cancer." (PMID 26836308, 2016). "Aberrant androgen receptor (AR)-dependent transcription is a hallmark of human prostate cancers." (PMID 27365400, 2016). "Preclinical models have shown that AR-FL and AR-V7 overexpression is associated with induction of a mesenchymal or stem-like phenotype known to promote metastasis, and death from prostate cancer is almost uniformly due to complications associated with metastasis." (PMID 27409172, 2016). "In addition to functioning as a transcription factor, experimental observations suggest that AR is also a licensing factor for AR-positive and androgen-sensitive prostate cancer cells and associates with licensing proteins Orc2, Cdc-6, Cdt-1 and Mcm2." (PMID 27835608, 2016). "Adding to the complexity, even the widely used AR + prostate cancer cell line LNCaP may have multiple AR genetic variants, and its androgen responsiveness is sensitive to passage number and culture conditions." (PMID 26936218, 2016). "However, castration resistance due to expression of constitutively active AR splice variants is a significant challenge to prostate cancer therapy; little is known why effectiveness of ADT can only last for a relatively short time." (PMID 26848868, 2016). "Consistent with SINT1 targeting AR AF-1, it attenuated transcriptional activities of both full-length AR and constitutively active AR splice variants, which correlated with inhibition of growth of enzalutamide-resistant prostate cancer cells expressing AR splice variants." (PMID 27576691, 2016). "The deficiency of AR increased the G1 phase in the prostate cancer cells." (PMID 27399684, 2016). "Androgen receptor mutations are observed in late stage prostate cancer." (PMID 27609145, 2016). "Remarkably, 5 induces apoptosis in human prostate cancer 22Rv1 cells (31.3% ± 8.2% apoptosis after treatment with 1 μM for 48 h), which are highly resistant to androgen receptor (AR)-targeted therapies due to a loss of the ligand-binding domain of the AR receptor." (PMID 27355960, 2016). "The chemoresistance map characterize the various underlying factors of prostate cancer associated chemo & radiation resistance, comprising docetaxel & paclitaxel resistance, radiation resistance, androgen receptor mediated signaling, neuroendocrine behavior and the role of transcription factors." (PMID 27476486, 2016).
prostate carcinoma (continued). "Increasing evidence suggests that the expression of AR variants is upregulated during castration-resistant progression of prostate cancer and that increased AR variant expression may contribute to anti-androgen therapy resistance." (PMID 27835608, 2016). "BAY 1024767 is a novel competitive AR antagonist that exhibits strong activity against AR wild-type and mutated forms found in therapy-resistant patients, keeps antagonistic activity with increased androgen stimulation and in prostate cancer models with elevated AR protein levels." (PMID 26760770, 2016). "The proteins encoded by these new AR variants could regulate androgen-responsive reporters in breast and prostate cancer cells under androgen-depleted conditions." (PMID 28035996, 2016). "Because FKBP52 is overexpressed in prostate cancer patients, it is feasible that overexpression of FKBP52 could be the cause of increased AR co-activation by β-catenin in prostate cancer." (PMID 26207810, 2015). "In this study, we compared AR levels in epithelial and stromal compartments of patient-matched benign and malignant prostate tissue, and demonstrate an association between low stromal AR levels and death from prostate cancer at one, three and five years post diagnosis." (PMID 25965833, 2015). "Present evidence suggests, in addition to activation of the classical AR target genes, constitutively active AR splice variants are associated with a distinct transcription program in prostate cancer cells as well as in prostate cancer xenografts displaying treatment-induced AR-Vs expression." (PMID 25481872, 2015). "Emergence of constitutively active AR variants may mediate growth and progression of prostate cancer in the castrate host and may confer resistance to new potent antiandrogens." (PMID 25950519, 2015). "Since AR inhibition is associated with autophagy induction, whether celastrol could induce autophagy in human prostate cancer cells was determined." (PMID 26473737, 2015). "Next, we analyzed the role of RUNX1 in prostate cancer cells and its association with AR." (PMID 25537508, 2015). "Since liver metastasis in prostate cancer represents an aggressive subset, these AR mutations, overexpression, amplification, and cross-talk mechanisms may explain the refractory nature of such patients to hormonal agents." (PMID 29147414, 2015). "Few studies linked the miRNAs to AR function in RCC progression even though recent reports demonstrated that some miRNAs might play a role in AR-mediated signals in prostate cancer progression." (PMID 26304926, 2015). "PRKAR1A is functionally linked to AR during the progression of prostate cancer." (PMID 25915538, 2015). "In addition, DACH1 associates with the estrogen and androgen receptors (ER and AR) to regulate signal transduction and proliferation of breast and prostate cancer cells." (PMID 25788272, 2015). "While it is known that AR positively correlates with an increased risk of developing prostate cancer, it is unknown whether antiandrogens can have an effect on bladder cancer." (PMID 26347776, 2015). "Recently AR has been implicated in the development and progression of breast and prostate cancers." (PMID 25781993, 2015). "In this context, many studies have focused on the molecular basis of prostate cancer and highlighted several alterations in well-characterized cancer pathways, the androgen/androgen receptor (AR) signaling, gene fusions or mutations directly related to gene expression, and chromatin regulation." (PMID 26267226, 2015). "The occurrence of ligand-independent, constitutively active androgen receptor splice variants in castration–resistant prostate cancer provides a conceptually simple explanation for the development of resistance to prostate cancer therapies that target the ligand-binding domain." (PMID 25481872, 2015).
prostate carcinoma (continued). "The AR, a member of the steroid receptor superfamily, is an X-linked nuclear receptor (NR) that is regarded as critical in sexual differentiation, gonadal maturation, maintenance of secondary male characteristics and the development of prostate cancer." (PMID 25434787, 2015). "Androgen receptor (AR) is one of the MF-CAN proteins associated to a disease pair showing a comorbidity pattern: prostate cancer (PC) and spinal and bulbar muscular atrophy (SBMA, ICD-9: 335.1), an illness leading to progressive muscle weakness and atrophy, known also as Kennedy's disease." (PMID 26157390, 2015). "We reasoned that HIF-1α might underlie this differential response of low-AR and high-AR prostate cancer cells due to its interaction with AR to form a ternary complex with β-catenin that is required for hypoxia-activated AR transactivation." (PMID 25821081, 2015). "Based on available evidence, the knockdown of FKBP52 is expected to significantly reduce AR signaling leading to a loss of proliferation in AR-dependent prostate cancer cells, which could prevent the selection of clonal populations." (PMID 26207810, 2015). "Thadani-Mulero and colleagues generated xenografts from two prostate cancer cell lines; LuCaP 86.2, which expresses predominantly the ARv567 splice variant of the androgen receptor (AR), and LuCaP 23.1, which expresses the full length AR as well as the ARv7 variant." (PMID 26401448, 2015). "Unfortunately, despite an initial response these approaches invariably fail due to aberrant AR signalling mediated by receptor mutations and splice variants, AR amplification and ligand-independent AR activation resulting in the development of castrate-resistant prostate cancer (CRPC)." (PMID 26462181, 2015). "In this study, we demonstrate that the second generation Hsp90 inhibitor AUY922 induces potent inhibition of AR transcription associated with antitumor activity, and increases cell death in combination with docetaxel in castrate resistant prostate cancer cell lines." (PMID 25072314, 2014). "Therefore a drug that inhibits the AR NTD would have potential therapeutic value for the treatment of advanced prostate cancer especially those cases that are resistant to current therapies and express constitutively active AR splice variants." (PMID 25268119, 2014). "Also shown are the cooperativity terms resolved for full-length AR, an AR point mutant associated with advanced prostate cancer (T877A) and GR." (PMID 24064251, 2014). "The huge progress made in the past few years to treat CRPC with hormonal manipulation or AR blockade caused confidence in prostate cancer therapy but may be compromised by resistance mechanisms acquired under these novel treatments." (PMID 25332874, 2014). "Recently, two lncRNAs, PCGEM1 and PRNCR1, have been suggested in prostate cancer to act as mediators of castration-resistance disease by binding, in a direct and sequential fashion, to the androgen receptor (AR), causing ligand-independent activation of its gene expression programs." (PMID 24727738, 2014). "Hence an antagonist of the NTD would be beneficial for prostate cancer patients that are failing current hormone therapies due to expression of constitutively active AR splice variants." (PMID 25268119, 2014). "With relevance to prostate cancer our previous investigations revealed an association of AR mRNA with the MID1 ribonuclear complex with AR mRNA via its trinucleotide repeat motifs and consequent upregulation of AR protein levels via this complex (unpublished results)." (PMID 24484909, 2014). "Thus, it is possible that SPOP mutations augment AR functions in prostate cancer by inhibiting turnover of both AR and its coactivator SRC-3." (PMID 24508459, 2014). "Overexpression of CAMK2N1 suppressed AKT and AR suggests that the loss of CAMK2N1 in advanced prostate cancer could be the primary cause of enhanced kinase signaling, which consequently leads to abnormal activation of AR." (PMID 25296973, 2014).
prostate carcinoma (continued). "As PCBP1 has been previously found to regulate the androgen receptor in androgen-responsive cells, like the prostate cancer LNCaP cells, this connection might be underlying the function of PCBP1 in ovarian tumor biology as well." (PMID 25265318, 2014). "Our identification of SPOP as a bona fide E3 ligase of the AR is highly relevant to prostate cancer, because SPOP-mediated degradation of AR protein is disrupted by its mutations identified in prostate cancer, as well as the majority of prostate cancer-derived AR splicing variants." (PMID 24508459, 2014). "However, increased androgen receptor growth is associated with the progression or switch of hormone sensitive cancers to hormone-resistant cancers, the more aggressive form of prostate cancer." (PMID 25533015, 2014). "Moreover, all SPOP mutations identified in human prostate cancers disrupt the SPOP-AR interaction and abolish SPOP-induced AR degradation." (PMID 24508459, 2014). "p-21 activated 6 (PAK6), first identified as interacting with the androgen receptor (AR), is over-expressed in multiple cancer tissues and has been linked to the progression of prostate cancer, however little is known about PAK6 function in the absence of AR signaling." (PMID 24352566, 2014). "The synergistic effects of AKT activation, overexpression of ERG and AR in basal cells closely recapitulated the histological and molecular features of human prostate cancer, with loss of basal cells and expansion of malignant luminal cells expressing PSA and AMACR." (PMID 23852643, 2013). "Moreover, Hsp90 is essential for the stability and function of numerous client proteins, a number of which have been causally implicated in the pathogenesis of prostate cancer, including the androgen receptor (AR)." (PMID 23152004, 2013). "In the present study we tested whether a) Casodex-induced telomere dysfunction is indeed mediated by AR, b) AR interaction with shelterin proteins occurs at telomeres, and c) AR inactivation causes telomere abnormalities in prostate cancer cells." (PMID 23363843, 2013). "In our research, we found that inhibition of Hsp90 with 17-AAG diminishes Slug level, possibly caused by proteasomal degradation of AR, which led to the suppression of cell migration and invasion in both androgen-sensitive and androgen-insensitive prostate cancer cell lines." (PMID 24130883, 2013). "Androgen receptor signaling is a key factor in many metastatic castration-resistant prostate cancers; the androgen receptor may be overexpressed, mutated, and possibly activated by the androgens produced by tumor cells in progressive disease." (PMID 25031999, 2013). "Given our findings that CCAR1 interacts with members of the NR family, such as ERα and glucocorticoid receptor (GR), we first examined the association between endogenous CCAR1 and AR in AR-positive LNCaP prostate cancer cells by coimmunoprecipitation (CoIP) assays." (PMID 23887938, 2013). "Castration-resistant growth of prostate cancer is often associated with increased expression of AR." (PMID 23437213, 2013). "We previously reported that AR phosphorylation at serine 213 was associated with poor outcome and may contribute to prostate cancer development and progression." (PMID 23945560, 2013). "This should be a better definition for AR gain and may allow identification of primary prostate cancer patients with high risk for disease progression." (PMID 24098661, 2013). "Indeed, it was reported that 10%–30% of prostate cancers treated by anti-androgens acquired point mutation in the AR gene." (PMID 23896594, 2013). "The AR-independent mechanisms include (e) mutations of tumor suppressor genes, (f) expression of various oncogenes affecting cell growth and death, (g) enhanced angiogenesis, (h) bypassing the AR pathway, and (i) prostate cancer stem cell regeneration." (PMID 23566222, 2013).